KDM3A (lysine demethylase 3A)
Diseases named in the same sentence as KDM3A in open-access papers (continued):
Sharing a sentence is not in itself a finding about the gene and the disease.
Obesity (19 papers, 2010 to 2025). Accumulation of substantial excess body fat. "Numerous enzymes associated with H3K9me3, the mark associated with heterochromatin, including acetyltransferases (SRC‐1/Ncoa1), deacetylases (Hdac3), methyltransferases (Suv39 h1 and G9a/Ehmt2), and demethylases (Jhmdh2a/Kdm3a, Jmjd2c/Kdm4c), have been linked to fatty liver, diabetes, and obesity." (PMID 29484800, 2018). "The human lysine (K)-specific demethylase 3A (KDM3A) is critically important in regulating the expression of metabolic genes and obesity resistance." (PMID 37108289, 2023). "KDM3A−/− mice have many of the signs of metabolic syndrome including insulin resistance, hypertriglyceridemia, elevated leptin levels, and obesity." (PMID 29922517, 2018). "In a corollary study, instead of artificially increasing H3K9 levels by knocking out KDM3A, obesity was induced dietetically in dams, and then the effect on H3K9 levels in offspring was examined." (PMID 29922517, 2018). "Eliminating KDM3A resulted in the expected increase in gene-silencing H3K9me2 levels, and indeed several genes related to anti-adipogenesis, obesity and T2D were downregulated in the knockout mice." (PMID 29922517, 2018). "KDM3A knockout mouse models are viable with only male germ cell defects and signs of early onset obesity." (PMID 25488809, 2015). "Eliminating the histone demethylase JHDM2A/KDM3A suggests that vulnerability to obesity and metabolic syndrome might result in disruptions in fat build-up and glucose processing." (PMID 40290121, 2025). "Moreover, loss of KDM3A in mice results in abnormal fat accumulation in WAT, obesity, and hyperlipidemia, suggesting that KDM3A is crucial for WAT browning." (PMID 34968255, 2021). "Kdm3a knockout mice have a defined metabolism and obesity phenotype, but the mice have never been examined with regards to the immune system." (PMID 24312603, 2013). "Kdm3a−/− mice show a phenotype related to metabolic gene expression and obesity but the effect on the immune system has not been reported." (PMID 24312603, 2013). "The Zhang laboratory has discovered that mice with systemic KDM3A deletion develop spontaneous obesity and hyperlipidemia largely due to a skewed metabolome in the adipose tissue, suggesting that targeting KDM3A globally to correct metabolic disorders may not be a desirable strategy." (PMID 32500071, 2020).
lung cancer (15 papers, 2015 to 2024). A malignant neoplasm involving the lung. "In the present paper, a part of the underlying mechanism in lung cancer was explained from the axis of miR-449a/KDM3A/HIF-1α." (PMID 34044859, 2021). "Therefore, the underlying regulatory mechanism of demethylase KDM3A on DCLK1 was further evaluated in lung cancer." (PMID 33350586, 2021). "Another miRNA, let-7i, delivered by EVs in lung cancer cells limited tumor cell proliferation via the KDM3A/DCLK1/FXYD3 axis." (PMID 39063032, 2024). "It was reported that SNHG4 promoted the progression of non‐small cell lung cancer (NSCLC) via modulating microRNA‐let‐7 e/KDM3A/p21 pathway." (PMID 36565037, 2023). "The results showed that LET-7i derived from BMSC-EV suppressed the inhibitory effect of DCLK1 on FXYD3 by down-regulating the expression of KDM3A, thus inhibiting the proliferation, migration and invasion of lung cancer cells." (PMID 35860555, 2022). "We also tested KDM3A expression in lung cancer tissues and cells, and found that KDM3A showed an increase in both lung cancer tissues and cells." (PMID 34044859, 2021). "In conclusion, our findings demonstrated that the BMSC‐EV‐derived let‐7i possesses an inhibitory role in lung cancer progression through the KDM3A/DCLK1/FXYD3 axis, suggesting a new molecular target for lung cancer treatment." (PMID 33350586, 2021). "According to a previous study, both KDM3A and DCLK1 can deteriorate the lung cancer, whilst KDM3A can promote the expression of DCLK1 through its demethylation modification." (PMID 33350586, 2021). "Collectively, these findings illustrated KDM3A as a tumour promoter in lung cancer through FXYD3 suppression by elevating DCLK1 via the removal of the methylation of H3K9me2 in the DCLK1 promoter region." (PMID 33350586, 2021). "Though we have confirmed the effects of miR-449a and KDM3A on lung cancer, and identified the targeting relation between miR-449a and KDM3A, as well as between KDM3A and HIF-1α, the internal mechanism of miR-449a/KDM3A/HIF-1α axis is not yet clear." (PMID 34044859, 2021). "Up-regulating KDM3A or HIF-1α negated up-regulated miR-449a-induced effects on cellular growth in lung cancer." (PMID 34044859, 2021). "The expression of KDM3A in lung cancer cell line A549 was also measured, and the results showed that compared with that in LL29 cells, KDM3A was highly expressed in lung cancer cell line A549." (PMID 33350586, 2021). "Collectively, miR-449a depressed KDM3A to incur tumor activities in lung cancer through down-regulating HIF-1α." (PMID 34044859, 2021). "The positive expression rate of the KDM3A in lung cancer tissues and paracancerous tissues was determined by the RT‐qPCR, and KDM3A was found to have a high expression in lung cancer tissues." (PMID 33350586, 2021). "Increased level of KDM3A has been shown in lung cancer and artificially silencing KDM3A obtains the ability to damage cell proliferation and migration." (PMID 34044859, 2021). "After loss‐ and gain‐of‐function assays, the effects of let‐7i, KDM3A, DCLK1 and FXYD3 on the biological characteristics of lung cancer cells were assessed." (PMID 33350586, 2021). "Subsequently, our results uncovered an aberrantly high expression of KDM3A in lung cancer cells whereas the repression of KDM3A induced by let‐7i resulted in the inhibition of lung cancer development." (PMID 33350586, 2021). "Then, it was revealed that restoring KDM3A or HIF-1α negated overexpressed miR-449a-induced effects on cellular growth in lung cancer." (PMID 34044859, 2021). "Accordingly, previous studies have showed the presence of a high expression of KDM3A in lung cancer cells, and thus, it is considered to be responsible for the development of lung cancer." (PMID 33350586, 2021). "To study the effects of KDM3A in lung cancer, we transfected oe-KDM3A and sh-KDM3A plasmids into A549 cells to up-regulate or down-regulate KDM3A expression." (PMID 34044859, 2021).
lung cancer (continued). "BMSC‐EV‐derived let‐7i resulted in the down‐regulation of KDM3A expression and reversed its promoting role in lung cancer development." (PMID 33350586, 2021). "In summary, our study provided evidence in support of the suppressive effects of BMSC‐EV‐derived let‐7i on the development of lung cancer cells through FXYD3 down‐regulation by increasing DCLK1 via KDM3A inhibition." (PMID 33350586, 2021). "The expression of KDM3A and proliferation, migration and invasion of lung cancer cells was detected." (PMID 33350586, 2021). "Not limited to lung cancer, the contributory effects of KDM3A overexpression are detected in other cancers." (PMID 34044859, 2021). "Shortly, up-regulating KDM3A promoted while down-regulating KDM3A suppressed the development of lung cancer." (PMID 34044859, 2021). "Then, inhibitor‐NC and let‐7i inhibitor were transfected into BMSC and added to lung cancer cells transfected with oe‐KDM3A after extracting BMSC‐EVs." (PMID 33350586, 2021). "It is eventually concluded that miR-449a delays lung cancer development through suppressing KDM3A/HIF-1α axis." (PMID 34044859, 2021). "As a result, compared with the treatment of PBS, the expression of KDM3A in lung cancer cells was notably reduced after treated by BMSC‐EVs." (PMID 33350586, 2021). "Functionally, KDM3A appeared to be equivalent to BRG1 in promoting lung cancer cell proliferation and migration." (PMID 31695026, 2019). "KDM3A knockdown achieved equivalent effects as BRG1 silencing by diminishing lung cancer proliferation and migration." (PMID 31695026, 2019). "Of note, KDM3A levels were elevated in malignant types of lung cancers paralleling BRG1 up-regulation." (PMID 31695026, 2019). "BRG1 activates transcription in lung cancer cells by recruiting the demethylase KDM3A and by directly up-regulating KDM3A expression." (PMID 31695026, 2019). "KDM3A is up-regulated by HIF-1α during hypoxia and KDM3A expression is elevated in both bladder and lung cancer." (PMID 25488809, 2015). "Additionally, previous studies have reported that KDM3A can be negatively regulated by miR-449a in lung cancer and activated by the transcription factor of HIF-1α in multiple myeloma." (PMID 37305393, 2023). "Following treatment with EVs, the expression of KDM3A in lung cancer cells was measured." (PMID 33350586, 2021). "Regarding to the functional roles of miR-449a, KDM3A and HIF-1α in lung cancer, this research was initiated to decode whether their integrity involved in lung cancer and targeting miR-449a/KDM3A/HIF-1α axis regulated cancer progression." (PMID 34044859, 2021). "miR-449a and KDM3A have been recorded to regulate lung cancer, respectively." (PMID 34044859, 2021). "Besides, KDM3A, validated as the target of miR-449a, was overexpressed in lung cancer and promoted cellular aggression." (PMID 34044859, 2021). "KDM3A is the mediator of biological progress in cancers and is up-regulated in lung cancer." (PMID 34044859, 2021). "Both lung cancer tissues and cells exhibited reduced miR-449a and raised KDM3A and HIF-1α levels." (PMID 34044859, 2021). "However, KDM3A overexpression impaired such anti-tumor effects of miR-449a on mice with lung cancer." (PMID 34044859, 2021). "Therefore, this study further explored miR-449a-mediated mechanism in lung cancer, mainly focusing on lysine demethylase 3A/hypoxia-induced factor-1α (KDM3A/HIF-1α) axis." (PMID 34044859, 2021). "Hence, BMSC‐EV‐derived let‐7i was identified as an inhibitor of the pathogenesis of lung cancer by suppressing the DCLK1/FXYD3 axis through KDM3A." (PMID 33350586, 2021). "A549 cells that had been transfected with the plasmids were injected into mice to study whether miR-449a/KDM3A/HIF-1α axis regulated lung cancer progression in vivo." (PMID 34044859, 2021).
lung cancer (continued). "Focused on the issue that whether KDM3A was involved in the process of miR-449a regulating lung cancer, we firstly determined the effect of miR-449a on KDM3A expression and found that overexpressing miR-449a decreased KDM3A level in cells." (PMID 34044859, 2021). "In addition, KDM3A is elevated in malignant type of human lung cancers and plays an essential role in hypoxia-induced lung cancer cell proliferation and migration." (PMID 31695026, 2019). "BMSC derived-evs could suppress lung cancer via KDM3A/DCLK1/FXYD3 axis." (PMID 38105218, 2023). "Moreover, IHC results further confirmed that KDM3A was overexpressed in lung cancer tissues." (PMID 33350586, 2021). "Compared with cells transfected with oe‐KDM3A, let‐7i in cells treated by oe‐KDM3A + EV‐inhibitor‐NC was notably increased; however, the KDM3A expression was significantly down‐regulated, whereas the proliferation, migration and invasion abilities of lung cancer cells were reduced." (PMID 33350586, 2021). "Thus, it could be concluded that elevating KDM3A or HIF-1α negated up-regulated miR-449a-induced suppression on cellular growth in lung cancer." (PMID 34044859, 2021). "Bioinformatic analysis tools were determinant to evaluate the role of a high expression of KDM3A (lysine demethylase 3A) and DCLK1 (doublecortin-like kinase 1) and reduced expression FXYD3 in lung cancer." (PMID 39769162, 2024). "The findings showed the presence of a high expression of KDM3A and DCLK1 and reduced expression of let‐7i and FXYD3 in lung cancer." (PMID 33350586, 2021). "On the whole, it is summarized that miR-449a interacts with KDM3A/HIF-1α axis, and performs anti-tumor effects on lung cancer." (PMID 34044859, 2021). "miR-449a, KDM3A and HIF-1α levels in lung cancer tissues and cell lines (A549, H1299 and H460) were measured." (PMID 34044859, 2021). "We report here that BRG1 recruits KDM3A to activate CCNB1 and LTBP2 transcription in lung cancer cells." (PMID 31695026, 2019). "From the axis of miR-449a/KDM3A/HIF-1α, the molecular mechanism of lung cancer has been further comprehended, and this axis may alight the potentials to treat lung cancer." (PMID 34044859, 2021). "Lysine demethylase 3A (KDM3A), also known as JMJD1A, is the overexpressed gene in lung cancer." (PMID 34044859, 2021). "The results indicated that compared with the cells transfected with si‐NC + oe‐NC, the expressions of KDM3A and DCLK1 in cells transfected with si‐KDM3A + oe‐NC were reduced, whereas proliferation, migration and invasion of lung cancer cells were notably reduced." (PMID 33350586, 2021). "Serving as a hypoxic response gene, KDM3A could be mediated by hypoxia-inducible factor-1α (HIF-1α), the key gene in lung cancer under a hypoxic microenvironment." (PMID 34044859, 2021). "Compared with cells transfected with si‐FXYD3, the expression of let‐7i and FXYD3 was enhanced in cells treated with si‐FXYD3 + EV‐mimic‐NC, the expression of KDM3A and DCLK1 was decreased, whereas the proliferation and invasion of lung cancer cells were inhibited, and the apoptosis was promoted." (PMID 33350586, 2021). "detected the expression of let-7i, lysine demethylase 3A (KDM3A), bicorticoid kinase 1 (DCLK1) and ion transport regulator 3 (FXYD3) containing FXYD domain in lung cancer tissues, then determined the regulatory relationship among them, and observed the effects of them on lung cancer cells." (PMID 35860555, 2022).
lung cancer (continued). "Furthermore, our results illustrated that KDM3A promotes the DCLK1 expression by binding to DCLK1 promoter and removing H3K9me2 modification, thereby promoting proliferation, migration and invasion of lung cancer cells." (PMID 33350586, 2021). "Our results revealed that compared with that of cells transfected with oe‐NC, let‐7i in cells transfected with oe‐KDM3A had no significant changes, whilst the expression of KDM3A was dramatically increased and lung cancer cell proliferation, migration, and invasion ability was promoted." (PMID 33350586, 2021).
colon carcinoma (13 papers, 2011 to 2025). "The deregulation of KDM3A has been reported in skin, hair, and cardiovascular diseases, as well as in multiple cancers, including breast, prostate, and colon cancers." (PMID 33888871, 2022). "Similar to the abnormally elevated expression of KDM3 in PCa, KDM3A is also overexpressed in colon cancer, and its levels are increased in colorectal cancer (CRC) metastatic lesions." (PMID 32354028, 2020). "Inhibits KDM3A overexpression in colon cancer cells and colon cancer organoids." (PMID 36975603, 2023). "In addition to its role in activating Wnt/β-catenin and Hippo signaling pathways in colon cancers, KDM3A activates the gene transcription of 15-lipoxygenase-1 (15-LOX-1), which is silenced in cancer cells." (PMID 32354028, 2020). "Histone H3 and histone H4 acetylation mediated by histone acetyltransferase lysine (K)-acetyltransferase 3B (KAT3B), and histone H3 dimethyl-lysine 9 (H3K9me2) demethylation catalysed by lysine (K)-specific demethylase 3A (KDM3A) transcriptionally activate ALOX15 in colon cancer cells." (PMID 24465480, 2014). "In colon carcinoma cells, hypoxia induces HIF-1 expression and in turn, HIF-1 induces Kdm3a expression." (PMID 29156681, 2017). "JMJD1A, also called lysine demethylase 3 A (KDM3A), can demethylate di- and monomethylated lysine 9 on histone H314 and may exert pro-oncogenic functions in colon cancer cells." (PMID 32457453, 2020).